MTOR (mechanistic target of rapamycin kinase)
Diseases named in the same sentence as MTOR in open-access papers (continued):
Sharing a sentence is not in itself a finding about the gene and the disease.
tumor (continued). "To elucidate the mechanism underlying the inhibition of tumor growth mediated by PostB, we examined the protein expression of autophagy pathway markers, such as PI3K, AKT, mTOR, TGF-β, and SMAD4, in the tumor tissues of CT26.WT-bearing mice by Western blotting." (PMID 39459634, 2024). "This may be related to the hypothesis that STL reduces tumor growth by inhibiting the PI3K/Akt/mTOR signaling pathway, which is a growth pathway that is active in multiple cancers." (PMID 38399266, 2024). "According to these findings, mTOR has a dual role in tumor angiogenesis." (PMID 39003350, 2024). "Finally, the radiation-induced upregulation of DDIT4, by acting as a negative regulator of mTOR, induces anti-tumor therapy resistance." (PMID 38339228, 2024). "In summary, our findings unveil an intricate signaling network involving METTL3/FGF2/PI3K/AKT/mTOR in LUAD and provide valuable insights into the molecular mechanisms underlying tumor progression, thus holding significant implications for targeted therapy and advancing LUAD research." (PMID 39497721, 2024). "Consequently, activation of the mTOR pathway improves and accelerates the generation, metastasis, proliferation, and angiogenesis of tumor cells." (PMID 39349424, 2024). "In this context, the PI3K/mTOR pathway has emerged as a central regulator of the tumour microenvironment (TME) and recent investigations have unveiled its potential contribution to ICB‐resistance in some epithelial tumour types, such as breast and colorectal cancer." (PMID 38711203, 2024). "In addition, the TUNEL assay was employed to evaluate tumor apoptosis levels and western blot was utilized to detect the mTOR/GLUT3 pathway-related protein expression to provide insights into the underlying mechanism." (PMID 39668819, 2024). "In addition, rapamycin is an FDA-approved drug known to inhibit the proliferation of tumor cells by blocking the mTOR signal." (PMID 38956724, 2024). "Furthermore, research has demonstrated that the estrogen receptor complex inhibits the mTOR signaling pathway, thereby impeding tumor growth." (PMID 38966543, 2024). "mTOR is a crucial regulator involved in tumor cell growth, proliferation, and survival." (PMID 39634548, 2024). "Suppression of fibronectin, vimentin, N-cadherin, MMP-9, MMP-2, twist, and snail.↑ Epithelial markers E-cadherin and Occludin levels.↓ Migratory and invasive potential of tumor cells by reversing epithelial-to-mesenchymal transition (EMT). ↓ PI3K/Akt/mTOR activation." (PMID 38611719, 2024). "The in vivo experimental results suggest that the anti‐PD‐L1 antibody may have a synergetic effect with the mTOR inhibitor in reducing tumor cell proliferation and that reduced PD‐L1 expression could contribute to antitumor efficacy." (PMID 38828669, 2024). "The growth mechanism of VS is well known to be associated with abnormalities in the Merlin protein, a tumor suppressor gene that activates receptor tyrosine kinases, such as ErbB, PDGF, VEGF, and C-kit, and activates the downstream pathways PI3K/AKT/mTOR and MEK-ERK1/2." (PMID 39766034, 2024). "The LKB1/AMPK/mTOR signaling pathway has been identified as a tumor suppressor axis in NSCLC." (PMID 39007099, 2024). "Tomatine treatment down‐regulated the PI3K/AKT/mTOR signaling pathway‐related proteins, suggesting that tomatine may play an anti‐tumor role by inhibiting autophagy and promoting apoptosis." (PMID 39155844, 2024). "Identification of WNT in the cell membrane may exclude the third grade of neoplasms, whereas the presence of cytoplasmic WNT and nuclear mTOR may indicate the third grade of neoplasms." (PMID 39188680, 2024). "mTOR also plays an important role in the glycolysis of tumor-infiltrating MDSCs." (PMID 39227970, 2024). "Interestingly, others have reported PD-L1’s indirect mediation of mTOR signaling by directly preventing the autophagy flux in tumor cells." (PMID 38892329, 2024). "The cytoplasmic expression of mTOR was evaluated in the VETC(+) areas of the tumor." (PMID 38250695, 2024).
tumor (continued). "An in-depth insight into many miRNA functions and their interplay with the P13K/AKT/mTOR pathway has revealed both oncogenic and tumor suppressor miRNAs, thus advancing the identification of surrogate biomarkers of drug sensitivity and potential miRNA-targeting agents." (PMID 38607050, 2024). "Conversely, inhibitors of amino acid transporters, such as 2-amino-2-norbornanecarboxylic acid (BCH) and KYT0353 (JPH203), have shown efficacy in reducing tumour size by pharmacologically inhibiting of Jh-21 in RasV12scrib−/− malignant tumours through mTOR signalling downregulation." (PMID 39682725, 2024). "With subcutaneous tumor formation and tail-vein injection assays, we demonstrate that overexpression of GP73 is critical for xenografting HCC tumorigenesis and metastasis triggered by mTOR activation in immune-deficient nude mice." (PMID 38459588, 2024). "The clinical impact of mTOR activation depends on the tumor type." (PMID 38673889, 2024). "UBE2T overexpression has been indicated to enhance the PI3K-AKT pathway activity in multiple cancers, worsening tumor malignancy by increasing the phosphorylation of key components, such as PI3K, Akt, and mTOR, and regulating downstream genes associated with cell survival and anti-apoptosis." (PMID 39791716, 2024). "The functional roles of PIK3R3 in CRC, to sustain cell proliferation (and presumably tumour growth), and the mTOR pathway were both disrupted following PIK3R3 knockdown, possibly reflecting the consequences of reduced PIK3R3 levels following metformin treatment." (PMID 38893174, 2024). "The candidates that were found had an enrichment in pathways associated with oncogenic signaling, particularly in variables that have been involved in the PI3K/AKT/mTOR signaling pathways which were identified using Tuba-sequencing or Tuba-seq (tumor barcoding with ultradeep barcode sequencing)." (PMID 38473324, 2024). "FGF19-FGFR4 signalling activates several pathways, including extracellular regulated protein kinases(ERK), jun N-terminal kinase (JNK), phosphoinositide 3-kinase (PI3K), mammalian target of rapamycin (mTOR) and others, which are closely related to tumour progression." (PMID 37782406, 2024). "By inhibiting PI3K/AKT/mTOR signaling, oxidative DNA damage, tumor‐specific markers, and the induction of caspase‐dependent apoptosis could be countered." (PMID 39524138, 2024). "The abnormally high expression of the HOXA1/AKT/mTOR signaling pathway may be one of the key factors leading to tumor occurrence and development." (PMID 38628206, 2024). "Recent genomic profiling efforts have provided deep understanding of molecular pathogenesis of HCC and a number of overactivated tumor driver pathways have been identified such as the Wnt and mTOR signaling pathways and but only a few are druggable targets by conventional treatment." (PMID 38696452, 2024). "Finally, studies show that KDs help avoid high blood glucose and insulin levels in response to treatment with PI3K, AKT or mTOR inhibitor (the so-called insulin-feedback) and cooperate with these agents in achieving optimal tumor growth control." (PMID 39064705, 2024). "The mTOR inhibitors play an important role in inducing tumour autophagic cell death (ACD)." (PMID 38757920, 2024). "However, the story turns riveting as the PI3K/AKT/mTOR narrative intersects with other signaling pathways in the tumor tropism saga." (PMID 39369580, 2024). "Taken together, high MAEL expression was identified as an independent indicator of poor benefits from ICI-based therapies over VEGFR/mTOR inhibitors in advanced ccRCCs, potentially mediated by tumor-infiltrating immune cells and the expression of PD-1 and CTLA-4 rather than PD-L1." (PMID 38301040, 2024). "The activation of the mTOR pathway can promote tumor growth, proliferation, and metastasis." (PMID 38482052, 2024).
tumor (continued). "In this study, arbutin may influence the intrinsic functions of PD-L1 by modulating the AKT/mTOR signaling pathway, potentially leading to decreased T/tumor cell proliferation and enhanced apoptosis." (PMID 39628695, 2024). "Recently, more specific, molecularly targeted drugs have been developed that block specific tumor cell survival pathways, such as mTOR-mediated pathway inhibitors, targeting the cell cycle and metabolism, and those affecting the tumor microenvironment, such as immunotherapies." (PMID 39409987, 2024). "The functions of mTOR signaling in immune cell regulation are diverse, on the one hand promoting T-cell accumulation and clearance in tumors, yet on the other hand, mediating tumor malignancy development and immune evasion." (PMID 38755125, 2024). "On the basis of the results of the gene enrichment analysis, the PI3K/mTOR/AKT signaling pathway is activated in uLMS via different mechanisms, including the amplification of mTOR, RICTOR, AKT, or insulin-like growth factor 1, as well as the loss of tumor suppressors such as PTEN." (PMID 39472980, 2024). "Importantly, co-inhibition of the MAPK and PI3K/AKT/mTOR pathways using a MEK inhibitor and everolimus, an mTOR inhibitor, showed a reduction in tumor burden in two different MPNST-forming GEMMs." (PMID 38473354, 2024). "There are growing experimental evidences that targeting mTOR and ferroptosis may have effective impact in many tumors, and understanding the mechanisms linking mTOR to ferroptosis could provide a potential therapeutic approach for tumor treatment." (PMID 38583115, 2024). "Upregulation of FASN enhances CRC growth and spread through the AMPK/mTOR signaling pathway and is associated with secondary lymph node involvement, tumor stage (TNM), and poorer CRC outcomes." (PMID 39119332, 2024). "By chemical inhibition, we could demonstrate a functional role for PI3K/Akt/mTOR to sustain tumor cell viability." (PMID 38191367, 2024). "EVE treatment reduced p-S6 levels across all genotypes, suggesting that EVE may effectively inhibit tumor growth by suppressing the mTOR pathway." (PMID 39736867, 2024). "Interestingly, the mTOR/MAPKAPK2/4EBP1/ZFP36L1 axis blunts both the pro-tumorigenic the tumour-suppressive effects of the SASP." (PMID 38317146, 2024). "For patient 22, we identified two tumor lineages with clonal drivers mutations in divergent pathways: a double ESR1Y537S,L536P mutation (ER pathway) in the tumor sample and an MTORT1977R mutation (PI3K/AKT/mTOR pathway) in the ctDNA sample." (PMID 38503755, 2024). "Notably, numerous clinical trials have demonstrated that selective kinase inhibitors like BRAF, MEK and mTOR inhibitors can restore RAI uptake in tumor cells." (PMID 39473507, 2024). "Activating the PI3K/AKT/mTOR signaling pathways increases the growth of tumor cells." (PMID 38592437, 2024). "Moreover, Akt-mTOR signaling facilitates angiogenesis, ensuring a sustained supply of nutrients and oxygen to the tumor." (PMID 39349425, 2024). "Previous studies have shown that EGFR mutations induce signaling pathways associated with carcinogenesis, such as PI3K/AKT/mTOR, RAS/RAF/MAPK, and JAK/STAT, and promote malignant phenotypes such as proliferation, survival, angiogenesis, invasion, and metastasis of tumor cells." (PMID 38243040, 2024). "Finally, the network pharmacological analysis of the processing biomarkers predicted that the key anti-tumor pathway of black ginseng was EGFR/PI3K/Akt/mTOR." (PMID 39200424, 2024). "Similarly, rapamycin has exhibited potent anticancer effects through the inhibition of mTOR signaling, leading to reduced tumor growth and metastasis." (PMID 38672078, 2024). "Therefore, IL-32γ overexpression induced autophagy in liver tumors through the suppression of MET and mTOR pathways critical for tumor growth inhibition." (PMID 39519229, 2024).
tumor (continued). "In HCC, sustained mTOR activation suppresses autophagy, which may contribute to tumor survival by preventing the clearance of damaged organelles and proteins." (PMID 39840041, 2024). "In vivo experimental results suggested that anti‐PD‐L1 antibody may have a synergetic effect with the mTOR inhibitor in reducing tumor cell proliferation and that reduced PD‐L1 expression could contribute to antitumor efficacy." (PMID 38828669, 2024). "Therefore, mTOR-targeted strategies to reduce tumor angiogenesis should be warranted for further understanding of the underlying mechanisms and optimizing antitumor function." (PMID 39003350, 2024). "At the mechanistic level, TOP2A can control tumor cell growth via AKT/mTOR pathway modulation." (PMID 38445610, 2024). "The PI3K/AKT signaling pathway is a pivotal axis for multiple upstream signaling in tumor cells, aggregating and regulating many downstream transcriptional targets, including mTOR (regulates HIF‐1α and c‐Myc on downstream), Forkhead box protein O1 (FoxO1), GSK3, and other key molecules." (PMID 39584783, 2024). "Indeed, PI3K/mTOR inhibition induced macrophage repolarisation towards an anti‐tumourigenic phenotype and increased antigen presentation on dendritic and tumour cells, but also promoted infiltration of PD‐1+ T cells displaying an exhausted phenotype." (PMID 38711203, 2024). "This holds significant relevance to uLMS, given the frequent dysregulation of this pathway (1/3 of cases), and some indications that hyper‐activation of the PI3K/mTOR pathway might contribute to resistance to ICB in this specific tumour type." (PMID 38711203, 2024). "The role of Akt/mTOR pathway in the anti-tumor effect of CARMN was explored." (PMID 39558374, 2024). "Therefore, a reversible chemoresistance phenotype can be stated to be regulated by the mTOR pathway, and the inhibition of mTOR signaling can be responsible for the tumor phenotype of the minimal residual disease following chemotherapy." (PMID 38418814, 2024). "The common involvement of the mTOR pathway genes has been demonstrated in this tumor, further supported by the expression of the mTOR pathway activation markers p-S6 and p-4EBP1; conversely, these tumors lack complete chromosomal gains or losses, as well as CCND1 rearrangements." (PMID 38791935, 2024). "ADH5 was expressed at the S351 phosphorylation site in tumor tissues with an altered mTOR pathway." (PMID 38600527, 2024). "In addition, PTEN is a typical tumor suppressor gene that inhibits the PI3K/Akt/mTOR signaling cascade, thereby increasing autophagy and reducing apoptosis." (PMID 38166086, 2024). "PI3K/AKT/mTOR pathway dysregulation is also very important in canine tumours." (PMID 38787171, 2024). "We hypothesize that mTOR inhibitors as inducers can effectively enhance the anti-tumor effect of MTAs in BC with HER2-low expression." (PMID 38344201, 2024). "The pathway of PI3K/AKT- mTOR will also lead to tumor progression." (PMID 38698848, 2024). "CD109 interacts with EGFR to activate the Akt/mTOR pathway, driving tumor growth." (PMID 39990858, 2024). "The PI3K/AKT/mTOR pathway can promote cell proliferation and tumor metastasis." (PMID 38318160, 2024). "We first assessed whether AKT (pAKT) activation was more frequently detected in tumours harbouring genetic alterations of the PIK3CA/AKT/mTOR axis compared to wild-type lesions using the IHC data." (PMID 39322687, 2024). "However, other molecular mechanisms of metformin that are AMPK-independent have been reported to be related to the oxygen consumption rate, tumor suppression, and blocking important pathways such as mTOR." (PMID 38675438, 2024). "PI3K/Akt/mTOR signaling pathway, one of the important pathways of regulating cell cycle, proliferation, apoptosis, differentiation and protein transport, has been a research hotspot of tumor cell biological behavior." (PMID 38544826, 2024).
tumor (continued). "C-X-C motif ligand 8 upregulates the expression of the PI3K/AKT/mTOR pathway in tumor cells, promotes the proliferation and epithelial-mesenchymal transition of tumor cells, and enhances the expression of PD-L1 on the BC cell membrane, which is detrimental to the long-term prognosis of patients." (PMID 39220365, 2024). "Our results indicate that the specific influence of DXS253E on the malignant proliferation of tumor cells may occur to some degree through effects on aerobic glycolysis via the AKT/mTOR pathway." (PMID 38890691, 2024). "In addition, the PD-1/PD-L1 signaling pathway inhibits the activation of the Akt and mTOR pathways in NK cells, leading to metabolic dysfunction and further weakening its anti-tumor effects." (PMID 39906665, 2024). "Interestingly, immunosuppression is correlated with tumor occurrence risk, some HCC pathways are also the target of some immunosuppression agents, such as the mammalian target of rapamycin (mTOR) inhibitors (mTORi)." (PMID 39840041, 2024). "Moreover, in the study of HNSCC cell line demonstrated the mTOR upregulation in the PD-L1 overexpression tumor cell line." (PMID 38370876, 2024). "The mTOR (mammalian target of rapamycin) signaling pathway is a key regulator of tumor metabolism." (PMID 39744011, 2024). "Furthermore, it has been reported that agents targeting the mTOR pathway can lead to significant inhibition of proliferation, differentiation, and tumor progression in PDAC." (PMID 38951899, 2024). "In addition, from the same research group, the authors used subcutaneous xenografts of uterine leiomyosarcomas from five patients and showed that dual PI3K/mTOR inhibition exhibits a strong reduction in tumor growth." (PMID 39682182, 2024). "An in vitro study of the dual PI3K/mTOR inhibitors, gedatolisib and PF-04691502, tested on 12 canine tumour cell lines (of 6 tumour types), found that gedatolisib decreased cell viability in a dose-dependent manner in all cell lines; however, some were more sensitive than others." (PMID 38787171, 2024). "This work proposes that EBV‐positive GC patients with mTOR/eIF4E hyperactivation may benefit from anti‐tumor immunotherapy." (PMID 38994917, 2024). "As a central signaling pathway hub, mTOR kinase plays an essential role in metabolic regulation to maintain the balance between anabolic and catabolic processes, including metabolic adaptation in stress responses and tumor cell survival." (PMID 38515456, 2024). "Serial echocardiographs are used to track the progressive effectiveness of the therapy, though a rebound in tumour size may occur after rapid discontinuation of mTOR inhibitors, necessitating close follow-up, even after complete regression of cardiac lesions." (PMID 39518472, 2024). "This suggests that genomic-independent activation of the signalling axis may affect PI3K/AKT/mTOR activity within the tumour microenvironment as a whole." (PMID 39322687, 2024). "Metformin also exhibits mTOR inhibitory functions, where the combined therapy could potentially enhance the anti-tumor effects of sapanisertib." (PMID 38892329, 2024). "Phosphorylation of mTOR was suppressed at various degrees in the tumor cells cultured with MASL." (PMID 39683650, 2024). "Moreover, in vivo results also indicated that pitavastatin reduced p-AKT and p-mTOR levels in tumor tissues of both NC and HFD conditions." (PMID 38319449, 2024). "By inhibiting the PI3K/mTOR pathway, echinacoside could effectively combat tumor cells and improve the outcomes." (PMID 38461536, 2024). "According to related studies, it was demonstrated that cell proliferation and migration decreased, and the tumor volume was also reduced by 55% in the T24-xenograft in vivo model through the inhibition of rpS6 phosphorylation and subsequent inactivation of the mTOR pathway." (PMID 39349424, 2024).